PART1 (prostate androgen-regulated transcript 1)
Synonyms: DKFZP586D0823; NCRNA00206
Gene: Long non-coding RNA gene on chromosome 5 (60,487,713 to 60,548,813, forward strand). Ensembl gene ENSG00000152931.
Diseases named in the same sentence as PART1 in open-access papers:
PART1 is named in the same sentence as 42 diseases in open-access papers, as found by Europe PMC text mining. Sharing a sentence is not in itself a finding about the gene and the disease. The quoted sentences say what the papers report.
prostate carcinoma (18 papers, 2001 to 2025). A carcinoma that arises from epithelial cells of the prostate gland. "Silencing PART1 is associated with a decrease in prostate cancer proliferation and apoptosis induction." (PMID 35773731, 2022). "PART1 promotes prostate cancer cell proliferation and inhibits cell apoptosis, and is associated with more advanced disease and poorer survival among prostate cancer patients." (PMID 34072264, 2021). "Growing evidence shows prostate androgen‐regulated transcript 1 (PART1) is considered as effective markers for prostate cancer, and has been shown to be associated with poor prognosis of NSCLC." (PMID 31436388, 2019). "PART1 is upregulated and its higher expression is associated with poor prognosis in prostate cancer and non-small cell lung cancer." (PMID 30755833, 2019). "The result revealed that 12.5, 25, 50, and 100 μmol/L inhibited the PART-1 expression, which regulated the transcriptome of prostate cancer." (PMID 40141034, 2025). "Each prostate cancer was treated with 5α-Dihydrotestosterone to induce the expression of the prostate androgen-regulated transcript-1 (PART-1), and only LNCaP expressed PART-1." (PMID 40141034, 2025). "As reported in previous studies, PART1 is a promising biomarker for predicting the prognosis in pancreatic cancer, non-small cell lung cancer, and prostate cancer." (PMID 39029955, 2024). "LncRNA prostate androgen-regulated transcript 1 (PART1) is an important lncRNA in the carcinogenesis whose role has been firstly unraveled in prostate cancer." (PMID 36875771, 2023). "Discovered in 2000, PART1 is expressed in prostate tissue and is responsive to androgens in prostate cancer cell lines." (PMID 34072264, 2021). "LncRNA PART1 (prostate androgen-regulated transcript 1) was originally considered as a tumor suppressor gene for prostate cancer due to its location on the chromosome 5q12.145." (PMID 34898376, 2021). "Given that PART1 has been shown to be responsive to androgens in prostate cancer cells, we suspected that the androgens in the cell culture media were influencing PART1 expression in breast cancer cells." (PMID 34072264, 2021). "The lncRNA prostate androgen-regulated transcript 1 (PART1) can regulate the proliferation and apoptosis of prostate cancer cells." (PMID 34484336, 2021). "A 2018 study showed that lncRNA PART1 modulates the toll-like receptor pathway to influence cell proliferation and apoptosis in prostate cancer cells." (PMID 31179185, 2019). "Here, we report additional characteristics of PART-1 tissue expression and hormonal regulation and study its expression profile in human normal and matched prostate cancer tissues." (PMID 11487271, 2001). "Prostate androgen regulated transcript 1 (PART-1), is a gene predominantly expressed in the prostate gland and is regulated by androgens in human prostate cancer cell lines." (PMID 11487271, 2001). "We used reverse transcriptase polymerase chain reaction (RT-PCR) to further characterize PART-1 tissue expression and hormonal regulation in the LNCaP prostate cancer cell line." (PMID 11487271, 2001). "LncRNA PART1 regulates nucleus pulposus cell degeneration through the miR-93/metalloproteinase-2 pathway, lncRNA-DLEU2 was implicated in the growth and development of tumors, and lncRNA-PCA3 was linked especially to prostate cancer." (PMID 34485379, 2021). "PART1 regulates prostate cancer cell proliferation and apoptosis." (PMID 34484336, 2021). "PART1 was regarded as a novel target in the treatment of prostate cancer." (PMID 34178478, 2021). "Moreover, PART1 upregulated by androgen is reported to promote cell proliferation and inhibit apoptosis via Toll-like receptor pathway in prostate cancer." (PMID 31367490, 2019). "Elevated PART1 promotes prostate cancer cell proliferation and inhibits cell apoptosis." (PMID 30755833, 2019). "PART1 can be used as a novel biomarker and target in the treatment of prostate cancer." (PMID 31179185, 2019).
prostate carcinoma (continued). "Specifically, in prostate cancer cells, supraphysiological androgen levels (SAL) up-regulate ADAMTS9-AS2 and down-regulate PART1." (PMID 40503765, 2025). "LncRNA PART1 is capable of inducing TLR signaling and its downstream targets including TLR3, TNFSF10 and CXCL13 in apoptosis inhibition in prostate cancer." (PMID 35773731, 2022). "Prostate androgen-regulated transcript 1 (PART1) lncRNA can regulate the proliferation and invasion of prostate cancer cells and breast cancer cells." (PMID 35740273, 2022). "There are fewer studies on PART1 than LNC00261, and only a few studies have investigated its role in prostate cancer and esophageal squamous cell carcinoma." (PMID 31179185, 2019). "Current research suggests that PART1 plays a dual role in cancer by regulating cell proliferation, apoptosis, invasion and metastasis through multiple potential mechanisms; that is, PART1 is upregulated in HCC, prostate cancer, and lung cancer and plays a role in promoting tumor growth." (PMID 39029955, 2024).
colorectal cancer (17 papers, 2018 to 2024). A primary or metastatic malignant neoplasm that affects the colon or rectum. "LncRNA PART-1 has been shown to have oncogenic activity in colorectal cancer, but was identified as positively associated with GBM prognosis, such that decreased PART-1 predicted decreased survival time." (PMID 33926464, 2021). "Studies on colorectal cancer have shown that the expression level of lncRNA PART1 is increased in cancer tissues and cells and that the proliferation and metastatic capacity of colorectal cancer cells are reduced after downregulation." (PMID 38807207, 2024). "Studies in clinical samples have shown up-regulation of PART1 in a variety of cancer tissues including bladder, breast and colorectal cancers." (PMID 36875771, 2023). "In colorectal cancer cells, three independent studies have shown possible mechanisms for contribution of PART1 in the carcinogenesis." (PMID 36875771, 2023). "Afterwards, the oncogenic function of PART1 had been validated in several types of human cancer including non-small cell lung cancer, colorectal cancer, and bladder cancer." (PMID 33865422, 2021). "In colorectal cancer, PART1 is oncogenic through possibly acting as miRNA sponge of miR-143 and regulating DNA methyltransferase 3A (DNMT3A)." (PMID 34072264, 2021). "Previous studies reported that PART1 expression was upregulated in non-small cell lung cancer, colorectal cancer, and bladder cancer." (PMID 33865422, 2021). "For example, miR-149-5p played a role in the has-circ-0005615/miR149-5p/TNKS axis in colorectal cancer and acted on the long noncoding RNA PART1/miR-149-5p/MAP 2K1 axis in hepatocellular carcinoma." (PMID 33224315, 2020). "Previous studies have shown that PART1 plays a tumor suppressive function in gliomas, but has a procancer effect in bladder cancer, non-small-cell lung cancer, and colorectal cancer." (PMID 32351983, 2020). "Recent studies have revealed that the lncRNA PART-1 was up-regulated in colorectal cancer, functioned as a competitive endogenous RNA to regulate the targeted gene DNMT3A by sponging miR-143, participated in colorectal cancer cell proliferation and metastasis." (PMID 29420609, 2018). "Reducing PART1 activity inhibited colorectal cancer cell proliferation and increased apoptosis." (PMID 37924077, 2023). "Finally, through sponging miR-150-5p, PART1 can increase expression of LRG1 in colorectal cancer cells." (PMID 36875771, 2023). "PART1 was shown to be overexpressed in colorectal cancer cell lines and tissues." (PMID 37924077, 2023). "Moreover, lncRNA PART1 functions as a carcinogenic pyrene in non-small-cell lung cancer and colorectal cancer." (PMID 34484336, 2021). "Similarly, PART1 was shown to promote malignant progression of colorectal cancer through the miR-150-5p/LRG1 axis and by sponging miR-150-5p to up-regulate the expression of CTNNB1 and activate Wnt/β-catenin signaling." (PMID 34072264, 2021). "In colorectal cancer, PART1 promotes tumor growth by acting as a ceRNA, sponging miR-143." (PMID 34072264, 2021). "Investigations in non-small cell lung cancer and colorectal cancer also showed that overexpression of PART1 markedly promoted tumor cell proliferation and epithelial–mesenchymal transition in vitro and accelerated tumor growth in mouse xenograft models in vivo." (PMID 34898376, 2021). "MiR-520h can be sponged by PART1 to overexpress CTNNB1, thereby regulating the development of colorectal cancer." (PMID 38394156, 2024). "Overexpression of PART1, SNHG11, LINC00173 and MIR17HG is widely involved in tumorigenesis and malignant progression of several types of cancer, such as glioma, breast cancer, lung cancer and colorectal cancer." (PMID 34243770, 2021). "Moreover, lncRNA PART1 is reported to function as a ceRNA to enhance CTNNB1 expression and activate Wnt/β-catenin pathway by competitively sponging miR-150-5p in colorectal cancer." (PMID 33680969, 2021).
esophageal squamous cell carcinoma (15 papers, 2014 to 2024). Esophageal squamous cell carcinoma (ESCC) is a type of esophageal carcinoma (EC) that can affect any part of the esophagus, but is usually located in the upper or middle third. "Diagnostic value of PART1 has been evaluated in the context of esophageal squamous cell carcinoma and lung squamous cell carcinoma." (PMID 36875771, 2023). "In esophageal squamous cell carcinoma cells, PART1 has been shown to acts as a tumor suppressor lncRNA in a single study." (PMID 36875771, 2023). "Furthermore, high levels of serum exosomal lncRNA PART1 in patients with esophageal squamous cell carcinoma (ESCC) are clinically associated with adverse reactions to gefitinib treatment." (PMID 36839784, 2023). "On the other hand, another study has shown that exosome-mediated transport of PART1 leads to induction of gefitinib resistance in esophageal squamous cell carcinoma cells through sponging miR-129." (PMID 36875771, 2023). "For instance, expression of PART1 has been shown to be decreased in esophageal squamous cell carcinoma tissues parallel with down-regulation of SOX6." (PMID 36875771, 2023). "LncRNA prostatic androgen-regulated transcription 1 (PART1) was transmitted by exosomes and taken by recipient cells, inducing resistance to gefitinib in esophageal squamous cell carcinoma (ESCC)." (PMID 37476905, 2023). "Elevated PART1 is found in esophageal squamous cell carcinoma and promotes gefitinib resistance by competitively binding to miR-129 to facilitate Bcl-2 expression." (PMID 31367490, 2019). "Prostate Androgen-Regulated transcript 1 (PART1) is a lncRNA that provokes gefitinib desensitization in esophageal squamous cell carcinoma." (PMID 31867576, 2019). "In esophageal squamous cell carcinoma (ESCC), elevated levels of exosomal lncRNA prostate androgen-regulated transcript 1 (PART1) caused resistance to gefitinib by binding to miR-129 and increasing the expression of Bcl-2." (PMID 31467934, 2019). "In contrast, PART1 is downregulated in esophageal squamous cell carcinoma and glioma and may suppress tumors." (PMID 39029955, 2024). "Up-regulation of PART1 could suppress cell proliferation and invasion, while its downregulation promotes cell proliferation and invasion in esophageal squamous cell carcinoma." (PMID 36875771, 2023). "In esophageal squamous cell carcinoma (ESCC), the lncRNA PART1 was enriched in exosomes and it acted as a ceRNA of miR-129 to upregulate Bcl-2 and promote gefitinib resistance." (PMID 39403602, 2024). "For instance, exosomal lncRNA PART1 amplifies esophageal squamous cell carcinoma (ESCC) cells’ resistance to gefitinib." (PMID 39188680, 2024). "Moreover, gefitinib-resistant esophageal squamous cell carcinoma (ESCC) cells express high levels of lncRNA Prostate Androgen-Regulated Transcript 1 (PART1)." (PMID 33920605, 2021).
glioma (15 papers, 2017 to 2024). A benign or malignant brain and spinal cord tumor that arises from glial cells (astrocytes, oligodendrocytes, ependymal cells). "In contrast to these studies, PART1 is part of lncRNA signature that predicts lower risk disease in glioblastoma and has been implicated as a tumor suppressor in glioma cells." (PMID 34072264, 2021). "For example, we constructed a lncRNA–miRNA–mRNA network to uncover the potential significance of Prostate Androgen-Regulated Transcript 1 (PART1)-hsa-mir-25-Talin 2 (TLN2)/Zinc Finger DHHC-Type Palmitoyltransferase 8 (ZDHHC8) in glioma." (PMID 39857625, 2024). "LncRNA PART1 is poorly expressed in glioma, and poor PART1 expression is negatively correlated with overall patient survival." (PMID 38807207, 2024). "For example, PART1 exerts tumor-suppressive functions in glioma via sponging miR-190a-3p and inactivation of the PTEN/AKT pathway." (PMID 35603200, 2022). "The interaction between PART1-hsa-mir-25-SLC12A5/TACC2/BSN/TLN2/ZDHHC8 is largely unclear in glioma and requires further analysis." (PMID 34660294, 2021). "Based on these results and the developed lncRNA-miRNA-mRNA regulatory network, we found that the PART1-hsa-miRNA-429-SHCBP1 signaling pathway plays an important role in glioma development." (PMID 32351983, 2020). "Our findings suggest the PART1-hsa-miR-429-SHCBP1 regulatory network plays an important role in gliomas." (PMID 32351983, 2020). "Similarly, PART1 has a tumor suppressor role in glioma through sponging miR-190a-3p and inactivating PTEN/AKT signals." (PMID 36875771, 2023). "lncRNA PART1 was reported to be significantly downregulated in glioma tissues and cell lines, and in the same study, PART1 promoted apoptosis and inhibited the proliferation of glioma cells by sponging miR-190a-3p, and subsequently upregulating PTEN and inactivating Akt signaling." (PMID 34202078, 2021). "LncRNA PART1 was downregulated in gliomas, and its overexpression in U87 cells induced cell growth arrest and apoptosis, indicating that it plays an anti-oncogenic role in glioma." (PMID 34660294, 2021). "Based on the bioinformatics analysis of a large number of glioma specimens, we found that PART1 and hsa-miRNA-429 could regulate SHCBP1 expression and that SHCBP1 can be used as a molecular biomarker to judge the prognosis of glioma patients." (PMID 32351983, 2020). "The PART1-hsa-miRNA-429-SHCBP1 signaling pathway may play an important role in glioma and provides a new direction for basic research into the underlying biology of gliomas." (PMID 32351983, 2020). "LncRNA PART1 can suppress glioma proliferation and migration via miR-374b/SALL1 axis, LINC00689 can inhibit glioma tumorigenesis via the miR-526b-3p/IGF2BP1 axis, GAS5 can alter the EMT process, proliferation, migration, and invasion of glioma cells through miR-106b targeting PTEN." (PMID 36425564, 2022). "Conversely, PART1 has tumor suppressive function in glioma by sponging miR-190a-3p, leading to upregulation miR-190a-3p target PTEN (a tumor suppressor), which subsequently inactivates the PI3K/AKT pathway in glioma cell lines." (PMID 34072264, 2021). "Neither lncRNA HCG11 nor PART1 have been investigated for a relationship with hsa-miR-129-5p and hsa-miR-490-3p in glioma." (PMID 33926464, 2021).
non-small cell lung carcinoma (14 papers, 2019 to 2024). A group of at least three distinct histological types of lung cancer, including non-small cell squamous cell carcinoma, adenocarcinoma, and large cell carcinoma. "As described in previous studies, high lncRNA PART1 expression is associated with poor prognosis and tumor recurrence in non-small cell lung cancer." (PMID 31367490, 2019). "In non-small cell lung cancer, the lncRNA PART1 has been reported to affect the tumorigenic ability of lung cancer cells in vivo through the JAK-STAT signaling pathway." (PMID 33193668, 2020). "A study found that PART1 could promote cell proliferation in non-small-cell lung cancer cells by targeting miR-17-5p." (PMID 34178478, 2021). "As a novel identified lncRNA, PART1 has been reported to be a promising biomarker for prediction of survival and tumor recurrence in stages I–III non-small cell lung cancer." (PMID 33865422, 2021).